LINC00671 (long independently transcribed non-coding RNA 671)
Gene: Long non-coding RNA gene on chromosome 17 (42,858,131 to 42,898,728, reverse strand). Ensembl gene ENSG00000213373.
Diseases named in the same sentence as LINC00671 in open-access papers:
LINC00671 is named in the same sentence as 4 diseases in open-access papers, as found by Europe PMC text mining. Sharing a sentence is not in itself a finding about the gene and the disease. The quoted sentences say what the papers report.
pancreatic cancer (1 paper, 2021). "Previous study reported that LINC00671 was downregulated in pancreatic cancerous tissues and serum, and silencing of LINC00671 promoted pancreatic cancer cell proliferation." (PMID 34404767, 2021).
thyroid cancer (1 paper, 2021). "STAT3/LINC00671/LDHA axis regulates thyroid cancer glycolysis, growth, and lung metastasis both in vitro and in vivo." (PMID 34404767, 2021). "Taken together, these results suggest that STAT3 increases proliferation, migration, and invasion of thyroid cancer cells and activates glycolysis via regulation of LINC00671 expression." (PMID 34404767, 2021). "LINC00671 or STAT3 activation may be useful for treatment of thyroid cancer with LDHA overexpression." (PMID 34404767, 2021). "Our research identified a novel STAT3/LINC00671/LDHA axis to regulate glycolysis, growth, and metastasis of thyroid cancer." (PMID 34404767, 2021). "Moreover, in thyroid cancer samples, STAT3 or LINC00671 expression is negatively correlated with LDHA expression as well as increased tumor FDG uptake." (PMID 34404767, 2021).
tumor (3 papers, 2021 to 2025). "LINC00671, which was linked to 17 mRNAs, has been widely reported as a tumor suppressor in various solid tumors." (PMID 36212177, 2022). "More importantly, the effect of LINC00671 knockdown on tumor growth was markedly abrogated when LDHA was knocked down." (PMID 34404767, 2021). "Taken together, these data suggest that LINC00671/LDHA axis regulates PTC tumor growth and lung metastasis in vivo." (PMID 34404767, 2021). "LINC00671 suppresses PTC tumor growth and metastasis through inhibition of LDHA-mediated Warburg effect." (PMID 34404767, 2021). "As expected, LINC00671 knockdown dramatically enhanced TC tumor growth." (PMID 34404767, 2021). "STAT3/LINC00671/LDHA axis regulates glycolysis, tumor growth, and lung metastasis of PTC both in vitro and in vivo." (PMID 34404767, 2021).
cancer (2 papers, 2022 to 2025). A tumor composed of atypical neoplastic, often pleomorphic cells that invade other tissues. "But LINC00671 has been reported serving as an anticarcinogenic role in various kinds of cancers." (PMID 36212177, 2022).